ENSG00000298544 (novel transcript)
Gene: Long non-coding RNA gene on chromosome 13 (44,904,978 to 44,923,757, reverse strand). Ensembl gene ENSG00000298544.
Gene Ontology:
Molecular function: triplet codon-amino acid adaptor activity
Biological process: translation